RNU6-1036P (RNA, U6 small nuclear 1036, pseudogene)
Gene: Small nuclear RNA gene on chromosome 5 (181,007,281 to 181,007,384, forward strand). Ensembl gene ENSG00000206686.
Homologues: Orthologues: chimpanzee U6 (98% identical), macaque U6 (93% identical), macaque U6 (91% identical), guinea pig U6 (89% identical), guinea pig U6 (87% identical), guinea pig U6 (84% identical), pig U6 (84% identical), pig U6 (83% identical). Paralogues in human: RNU6-1316P (91% identical), RNU6-35P (91% identical), RNU6-1145P (90% identical), RNU6-38P (90% identical), RNU6-20P (89% identical), RNU6-434P (89% identical), RNU6-698P (89% identical), RNU6-1031P (88% identical), RNU6-16P (88% identical), RNU6-25P (88% identical), RNU6-29P (88% identical), RNU6-393P (88% identical), and 1288 more.